HLA-G (major histocompatibility complex, class I, G)
Diseases named in the same sentence as HLA-G in open-access papers (continued):
Sharing a sentence is not in itself a finding about the gene and the disease.
vitiligo (3 papers, 2010 to 2023). Generalized well circumscribed patches of leukoderma that are generally distributed over symmetric body locations and is due to autoimmune destruction of melanocytes. "Once the inhibitory properties of HLA-G depend on the interaction with its receptors, the present study has evaluated both univariate and multivariate associations with vitiligo." (PMID 36831297, 2023). "Here we investigated the LILRB1 and LILRB2 association with vitiligo risk and evaluated the possible role of interactions between HLA-G and its receptors in this pathogenesis." (PMID 36831297, 2023). "It has been suggested that HLA-G, a key immunoregulatory molecule, may play a role in vitiligo susceptibility." (PMID 36831297, 2023). "However, no study has evaluated the role of LILRB1 and LILRB2 polymorphisms in developing vitiligo or the possible interactions between HLA-G and the genes encoding its receptors." (PMID 36831297, 2023). "However, the possible association of HLA-G gene polymorphisms with vitiligo has been investigated so far only in the Korean population." (PMID 31505868, 2019). "The role of HLA-G polymorphisms, whose molecule presents an immunomodulatory feature, in the susceptibility to vitiligo is unknown." (PMID 31505868, 2019). "Despite the latest advances in vitiligo, the role of the simultaneous genetic composition of HLA-G, LILRB1, and LILRB2 in disease development remains to be elucidated." (PMID 36831297, 2023). "We tested the association of the polymorphisms of HLA-G, LILRB1, and LILRB2 with vitiligo using logistic regression along with adjustment by ancestry." (PMID 36831297, 2023). "Here we evaluated HLA-G variability in vitiligo patients and controls surveyed in southeastern Brazil, adjusting for population stratification by using AIMs." (PMID 31505868, 2019). "Besides uncovering HLA-G as a possible causal gene involved in vitiligo pathogenesis, the present results may either reinforce the importance of HLA-A*02 alleles in the vitiligo pathogenesis, even in admixed populations, or refute the previous conclusion that HLA-A*02:01 is involved in this disease." (PMID 31505868, 2019). "In the present study, 22 vitiligo patients and 24 healthy controls were investigated to look for a possible correlation between HLA-G expression and this pathology." (PMID 20418972, 2010). "Moreover, a consistent second-order combination involving HLA-G (rs9380142) and LILRB1 (rs2114511) was identified, indicating an epistatic interaction role between HLA-G and LILRB1 alleles in vitiligo pathogenesis." (PMID 36831297, 2023). "Another hypothesis is that HLA-G expressed on the skin of vitiligo patients interacts with KIR2DL4 receptors from NK cells, and this interaction may induce the production of proinflammatory cytokines such as IFN-γ, TNF-α, IL-1α, IL-1β, IL-6, and IL-8." (PMID 31505868, 2019). "Although these HLA-G polymorphisms have been associated with non-segmental vitiligo, authors do not analyze the whole genetic diversity of the HLA-G gene." (PMID 31505868, 2019). "However, HLA-G expression in biopsy specimens has been negatively correlated with vitiligo among Tunisians." (PMID 31505868, 2019). "Furthermore, HLA-G expression has been negatively correlated with vitiligo among Tunisians, a finding that reinforces the possible influence of HLA-G on vitiligo development." (PMID 31505868, 2019). "Therefore, the expression of HLA-G was likely deactivated during the process of vitiligo." (PMID 20418972, 2010). "The present study supports the hypothesis that negative HLA-G expression is associated with vitiligo." (PMID 20418972, 2010). "Therefore, it is not clear whether HLA-G gene polymorphisms and ligands may influence the susceptibility to vitiligo." (PMID 31505868, 2019).
vitiligo (continued). "Thus, assuming that G*01:01:01:01/UTR-1 is a high HLA-G producer, the associations observed here are not consistent with our hypothesis that a lower HLA-G production would result in a stronger autoimmune response and, therefore, would be associated with vitiligo." (PMID 31505868, 2019). "It remains to be understood why some vitiligo patients express HLA-G, whereas, other negative controls didn't develop vitiligo." (PMID 20418972, 2010). "Accordingly, whether or not individual polymorphisms in HLA-G, LILRB1, and LILRB2 were associated with susceptibility to vitiligo and whether or not there were some epistatic interactions between them were, therefore, investigated here." (PMID 36831297, 2023). "There is significant negative correlation between HLA-G expression and vitiligo." (PMID 20418972, 2010). "There was no case of extensive vitiligo between HLA-G-positive vitiligo patients." (PMID 20418972, 2010). "Thus, additional HLA-G regulatory variation sites may influence the development of non-segmental vitiligo." (PMID 31505868, 2019).
AIDS (2 papers, 2010 to 2020). A syndrome resulting from the acquired deficiency of cellular immunity caused by the human immunodeficiency virus (HIV). "We evaluated whether HLA-G 3′UTR influences CMV-R development in Brazilian AIDS patients." (PMID 33122781, 2020). "No literature data have been reported regarding the variability at the 3′UTR of the HLA-G gene in patients with AIDS, exhibiting or not CMV-R." (PMID 33122781, 2020). "Although studies regarding the classical HLA class I and class II profiles of patients with AIDS exhibiting ocular manifestations have been reported so far17–19, there is no information regarding the study of the non-classical HLA-G gene in patients exhibiting both AIDS and CMV-R." (PMID 33122781, 2020). "The present study was undertaken based on the hypothesis that variation sites at the HLA-G 3′UTR in patients with AIDS exhibiting or not CMV-R may discriminate variation sites associated with the regulation of the immune checkpoint gene." (PMID 33122781, 2020).
antiphospholipid syndrome (2 papers, 2012 to 2019). A disorder caused by the presence of autoantibodies directed against phospholipids, causing a hypercoaguable state, which may result in blood clots, stroke, heart attack, and in women, significant pregnancy-related complications, including miscarriage and still birth. "The HLA-G 10101 and the HLA-G 10106 alleles, on the other hand, may reduce the risk of antiphospholipid syndrome." (PMID 30893814, 2019). "Serum HLA-G levels are increased in antiphospholipid syndrome patients in comparison to healthy controls." (PMID 22654952, 2012). "Heparin treatment increases HLA-G levels in antiphospholipid syndrome patients with obstetric events." (PMID 22654952, 2012).
aplastic anaemia (2 papers, 2023 to 2025). "HLA-G- Ig-like transcript 2 (ILT2) interaction has been reported to cause a decrease in bone marrow B cell function, leading to acquired aplastic anaemia." (PMID 40953010, 2025). "Another ubiquitin-containing protein to be classified within exosomes is the non-classical human leukocyte antigen G (HLA-G); exosomes isolated from ascites and pleural exudates of patients with aplastic anemia HLA-G-positive showed that this protein was enriched by ubiquitin." (PMID 37763246, 2023).
arbovirus infection (2 papers, 2021 to 2025). A viral infection that is transmitted by an arthropod. "Initially, we evaluated the role of the immune checkpoint HLA-G molecule on arbovirus infections and its relationship with cytokines, chemokines, and growth factors." (PMID 33776990, 2021).
autoimmune hepatitis (2 papers, 2022 to 2025). Hepatitis caused by autoantibodies. "The immunomodulatory effects of HLA-G expression and its role in cancers, human liver infections and liver transplantation are well documented, but so far, there are only a few reports addressing autoimmune liver diseases, particularly autoimmune hepatitis (AIH)." (PMID 36311782, 2022).
Burkitt lymphoma (2 papers, 2016 to 2022). A rare form of malignant mature B-cell non-Hodgkin lymphoma. "It is noteworthy that EBV infections can be linked to various tumor entities, such as NPC, gastric adenocarcinoma (GC), classical Hodgkin lymphoma (cHL) and Burkitt lymphoma (BL), which have been shown to exhibit pathophysiological HLA-G neoexpression." (PMID 35237271, 2022). "The EBV positive and negative Burkitt's lymphoma B cell lines Daudi and BJAB, the embryonic kidney cell line HEK293T and an HLA-G transfected EBV transformed B cell line 721.221 did not induce the expression of GFP in the LILRB3 reporter 2B4 cells." (PMID 26769854, 2016).
chronic graft versus host disease (2 papers, 2022 to 2023). Chronic graft versus host disease (GVHD) is a complication that can occur after a stem cell or bone marrow transplant in which the newly transplanted donor cells attack the transplant recipient's body. "Our results revealed that two SNPs (rs371194629 and rs9380142) and one haplotype (UTR-3) located in the 3’-UTR and two SNPs (rs3823321 and rs1736934) and one haplotype (G0104a) located in the 5’-URR of HLA-G were associated with the occurrence of chronic GVHD or development of any forms of GVHD." (PMID 36911734, 2023).
chronic hepatitis (2 papers, 2015 to 2021). An active inflammatory process affecting the liver for more than six months. "Such regulation of the immune system facilitates mast cells and activates HLA-G molecules, which are involved in the pathology of chronic hepatitis." (PMID 34488768, 2021).
Cirrhosis (2 papers, 2022 to 2023). A chronic disorder of the liver in which liver tissue becomes scarred and is partially replaced by regenerative nodules and fibrotic tissue resulting in loss of liver function. "Here, we establish the presence, regulation and mechanism of action of a suppressive CD4+ T cell subset expressing human leucocyte antigen G (HLA-G) in patients with acute decompensation of cirrhosis (AD)." (PMID 34344786, 2022). "Flow cytometry was used to determine the proportion and immunophenotype of CD4+HLA-G+ T cells from peripheral blood of 20 healthy controls (HCs) and 98 patients with cirrhosis (28 with stable cirrhosis (SC), 20 with chronic decompensated cirrhosis (CD) and 50 with AD)." (PMID 34344786, 2022).
co-infection (2 papers, 2018 to 2020). "Moreover, some have focused on the association between HLA-G 3′UTR polymorphisms and HPV infection among HIV-positive women who have a higher risk of developing HPV co-infection." (PMID 32670296, 2020). "Allelict and genotypic frequencies of HLA-G 3’ untranslated region (3’UTR) polymorphic sites of the HLA-G gene in the controls group and in HIV-infected women stratified according to the presence of HIV/HPV co-infection." (PMID 30278059, 2018). "In resume, we showed that the +3142G and +3187A alleles, which are related to low HLA-G expression, were associated with predisposition to HIV infection independent of the presence of HIV/HPV co-infection, but HIV induces the production of HLA-G in untreated patients through unclear mechanisms." (PMID 30278059, 2018).
colorectal tumor (2 papers, 2022 to 2023). "Furthermore, both inter- and intratumour heterogeneity have been reported for HLA-G in colorectal tumours." (PMID 35027037, 2022).
cutaneous melanoma (2 papers, 2021 to 2023). A primary melanoma arising from atypical melanocytes in the skin. "NKG2A is, contrary to primary NK cells, one of the few inhibitory receptors expressed by CD276-CAR NK-92 cells and their respective tumor cell ligands, HLA-E and HLA-G, are commonly overexpressed in cutaneous melanoma." (PMID 33925968, 2021).
embryonal carcinoma (2 papers, 2020 to 2021). A non-seminomatous malignant germ cell tumor characterized by the presence of large germ cells with abundant cytoplasm resembling epithelial cells, geographic necrosis, high mitotic activity, and pseudoglandular and pseudopapillary structures formation. "The embryonal carcinoma cell line, 2102Ep, or primary decidual stromal cells were used as a positive control for HLA-A, -B and -C expression and also served as a negative control for HLA-G." (PMID 34651188, 2021).
endothelial dysfunction (2 papers, 2014 to 2025). In vascular diseases, endothelial dysfunction is a systemic pathological state of the endothelium (the inner lining of blood vessels) and can be broadly defined as an imbalance between vasodilating and vasoconstricting substances produced by (or acting on) the endothelium. "HBP plays an important role in macrovascular complications of DM2; it is a manifestation of endothelial dysfunction involving the insertion of 14 bp polymorphism in HLA-G." (PMID 24689061, 2014). "Hypoxia-inducible factor 1 alpha (HIF-α) dysregulation contributes to alterations in matrix metalloproteinases (MMPs), cytokines, and endothelins (ETs) and aberrations in CD31+ cells and soluble HLA-G, resulting in endothelial dysfunction and reduced trophoblast invasion." (PMID 41515555, 2025).
fibrosis (2 papers, 2021 to 2022). the formation of excess fibrous connective tissue in an organ or tissue in a reparative or reactive process. "An initial immunohistochemistry study was performed on a series of alcohol-induced fibrosis samples (n = 41), allowing the enumeration of HLA-G+ and CD117+ cells over the entire slides by semi-automatic enumeration using HALO software." (PMID 34830373, 2021).
gastric tumor (2 papers, 2024). "Previous research has documented HLA-G expression in gastric tumors." (PMID 39549048, 2024).
heart transplant (2 papers, 2014 to 2019). "Increased soluble level of HLA-G with expression of HLA-G in endomyocardial biopsy was reported to be associated with lower incidence of rejection episodes in heart transplant recipients." (PMID 24591768, 2014).
hepatitis B (2 papers, 2015 to 2016). "Six of 16 designated HLA-E, HLA-G, and HLA-F haplotypes were shown to be associated with risk for hepatitis B or HCC." (PMID 27243039, 2016). "Four SNPs (rs17875380, rs41557518, rs114465251, and rs115492845), in nonclassical class I alleles, were shown to be associated with altered susceptibility to HBV or HCC, while HLA-F ∗01:04, HLA-G ∗01:05N, and HLA-E ∗01:01 are associated with hepatitis B or hepatitis B complicated with HCC." (PMID 27243039, 2016).
hepatitis C virus (2 papers, 2020 to 2023). "Of interest, in patients with SCD, a genetic variant in the MHC class II molecule, MHC HLA-G +3142, showed increased susceptibility to hepatitis C virus infection." (PMID 36926339, 2023).
human African trypanosomiasis (2 papers, 2022 to 2026). A parasitic disorder caused by protozoa of the Trypanosoma brucei species. "In the context of human African trypanosomiasis (HAT), higher soluble HLA-G levels were detected in the plasma of confirmed cases, representing a serological marker of T. b. gambiense infection." (PMID 41802004, 2026).
influenza (2 papers, 2014 to 2022). An acute viral infection of the respiratory tract, occurring in isolated cases, in epidemics, or in pandemics; it is caused by serologically different strains of viruses (influenzaviruses) designated A, B, and C, has a 3-day incubation period, and usually lasts for 3 to 10 days. "A comparable staining pattern, but statistically significant higher HLA-G expression levels were found in SARS-CoV-2- compared to lung tissues from influenza-infected patients." (PMID 36334153, 2022).
Insulin resistance (2 papers, 2022 to 2024). Increased resistance towards insulin, that is, diminished effectiveness of insulin in reducing blood glucose levels. "Moreover, the HLA-G 14bp ins/ins genotype is associated with insulin resistance, birth weight, and placental weight." (PMID 36532068, 2022).
invasive breast ductal carcinoma (2 papers, 2013 to 2023). "Also, in Brazilians, the Del/Del genotype is associated with higher levels of soluble HLA-G in invasive breast ductal carcinoma, poor prognosis of life and metastasis." (PMID 37623251, 2023).
latent infection (2 papers, 2017). "There were suggestive associations at three loci in IL6 and TNFA in the comparison between active cases and controls, one SNP in each of APOL1, MIF and IL6 in the comparison between latent infections and active cases and seven SNP in IL4, HLA-G and TNFA between latent infections and controls." (PMID 29059176, 2017).
liver cancer (2 papers, 2011 to 2021). An epithelial or non-epithelial malignant neoplasm that arises from the liver. "As a critical process that evolves in the TME, hypoxia affects epithelial-mesenchymal transition and angiogenesis and mainly changes the expression of immune checkpoint molecules, such as PD-L1, CD47, PD-1, and HLA-G, in liver cancer." (PMID 33596985, 2021).
Lung Disease (2 papers, 2022). "We show here for the first time that patients infected with the SARS-CoV-2 and pulmonary disease had a high frequency of membranous HLA-G expression in the lung tissues, predominantly the alveocytes, but not in other tissues suggesting an organ-specific HLA-G neo-expression." (PMID 36334153, 2022).
lymphopenia (2 papers, 2021 to 2022). Reduction in the number of lymphocytes. "Therefore, one of the possibilities is that HLA-G CAR-NK may damage HLA-G-expressing tissues, resulting in lymphopenia or respiratory disorder." (PMID 34663641, 2021).
metastatic tumor (2 papers, 2016 to 2021). "The mean value of soluble HLA-G was 49.04 ng/mL, and the level of HLA G varied greatly in metastatic tumors." (PMID 34868081, 2021). "Over the years, many studies have reported that HLA-G is preferentially detected in the primary tumor site and metastatic tumor site, while it is rarely detected in the tumor spontaneous regression site, adjacent tissues, or healthy tissues." (PMID 34868081, 2021). "Surprisingly, expression of HLA-G (in 83 % of the cases) in the metastatic tumor cells was also significantly more often present in cases without parametrium involvement (P = 0.034, Chi2 test)." (PMID 27895918, 2016). "In previous studies, HLA-G expression was found in 27–30 % of the primary- and 11 % of the metastatic tumor samples, but without histological subtyping." (PMID 27895918, 2016).
myositis (2 papers, 2021 to 2025). "Dysregulation of HLA genes including HLA‐DQA1, HLA‐A, and HLA‐G are described in DM patients and HLA gene polymorphisms were shown to be susceptibility factors in myositis." (PMID 34043263, 2021). "HLA-G (pos) T cells are found in inflamed skeletal muscle in myositis and the cerebrospinal fluid in people with acute inflammatory disorders." (PMID 40270514, 2025).
ovarian endometriosis (2 papers, 2010 to 2021). A non-neoplastic disorder characterized by the growth of endometrial tissue in the ovaries. "Similarly, HLA-G levels differ between patients with uLM and patients with ovarian endometriosis, although these levels are greatly dependent on the phase of the menstrual cycle, which limits their clinical potential." (PMID 34445194, 2021). "In our previous studies we have demonstrated that both the expression of RCAS1 and HLA-G in ovarian endometriosis and its concentration in the peripheral blood does not differ between the proliferative and secretory cycle phases." (PMID 20923543, 2010).
polycythaemia vera (2 papers, 2014 to 2024). "In the myeloproliferative neoplasm (MPN) polycythemia vera (PV), it has been shown that HLA-G inhibits the formation of PV patient derived erythropoietin-independent erythroid colonies and decreased the proliferation of UT7/EPO and HEL cell lines." (PMID 39696628, 2024). "In agreement with this HLA-G antitumor activity in B cell malignancies, we previously showed that soluble HLA-G inhibits the growth of erythropoietin (EPO)-independent colonies in patients suffering from polycythaemia vera." (PMID 24800261, 2014).